IGF2BP2 (insulin like growth factor 2 mRNA binding protein 2)
Diseases named in the same sentence as IGF2BP2 in open-access papers (continued):
Sharing a sentence is not in itself a finding about the gene and the disease.
Obesity (30 papers, 2010 to 2025). Accumulation of substantial excess body fat. "IGF2BP2 rs4402960 is also associated with lower fasting insulin level and impaired β-cell function, both associated with obesity." (PMID 33568150, 2021). "Ning Dai focused on the associations and mechanism underlying expression of IGF2BP2 SNPs and the development of metabolic diseases including T2D, nonalcoholic steatohepatitis, obesity and fatty liver disease." (PMID 33568150, 2021). "Our study is the first analysis of the interaction of obesity and IGF2BP2 variant on T2DM susceptibility." (PMID 25062844, 2014). "Since some variants are known to affect the risk of T2DM through obesity, this work aimed to evaluate the interaction effect of IGF2BP2 and obesity on T2DM susceptibility." (PMID 25062844, 2014). "Inactivation of the Igf2bp2 gene caused a resistance to diet-induced obesity in mice." (PMID 27835940, 2016). "IGF2BP2 rs4402960 G > T variant is associated with predisposition to T2D and obesity." (PMID 25612568, 2015). "Potential obesity and T2D-related genetic variants that may influence athletic performance as well are located in the IGF2BP2, LPL, KCJN, and MTHFR genes." (PMID 25612568, 2015). "We studied the association between five obesity and co-morbidities-related genetic variants (IGF2BP2 rs4402960, LPL rs320, LPL rs328, KCJN rs5219, and MTHFR rs1801133) and athletic status in a well-defined (athletic level, ethnicity, gender) athletic population." (PMID 25612568, 2015). "Since some genetic variants are known to affect the risk of T2DM through obesity, a hypothesis comes up that IGF2BP2 may have a relationship with obesity." (PMID 25062844, 2014). "In analyses using full covariate models, we observed that the T T2D-risk allele at the IGF2BP2 SNP rs4402960 was associated with raised fasting glucose level (p = 0.045), and that the A obesity-risk allele at the FTO SNP rs9939609 was associated with raised BMI (p = 0.003)." (PMID 20929593, 2010). "Moreover, previous studies have shown that polymorphisms in the insulin-like growth factor 2 mRNA binding protein 2 (IGF2BP2) gene may be a risk factor for obesity and T2DM." (PMID 39659616, 2024). "For instance, IGF2BP2 is essential for early commitment of adipocyte-derived stem cells into preadipocytes, and mice with IGF2BP2 deletion in MSCs exhibit resistance to diet-induced obesity." (PMID 38196046, 2024). "In fact, IGF2BP2 plays an important role in the occurrence of metabolic diseases such as obesity, T2D, and cancers." (PMID 39214307, 2024). "The expressions of GAS5, fat mass and obesity-associated protein (FTO), insulin-like growth factor 2 mRNA-binding protein 2 (IGF2BP2), and Quaking (QKI) were assessed by quantitative reverse transcription-polymerase chain reaction (qRT-PCR) and western blot." (PMID 38782769, 2024). "In this study, we found that HF resists high-fat diet (HFD)-induced obesity by binding to IGF2BP2 and promoting Bim m6A modification-mediated apoptosis in adipocytes." (PMID 39214307, 2024). "Reporter assay revealed that insulin-like growth factor 2 mRNA-binding protein 2 (IGF2BP2/IMP2) is a type 2 diabetes- and obesity-associated gene that suppresses Ucp1 mRNA translation likely via both 5′- and 3′-UTRs." (PMID 33634052, 2020). "In this regard, inactivation of the IGF2BP2 in mice induces resistance to diet-induced obesity and fatty liver due in part to increased energy expenditure, suggesting that IGF2BP2 has an important role in the regulation of energy homeostasis." (PMID 31333715, 2019). "The intron 2 G > T substitution in the IGF2BP2 rs4402960 is particularly interesting and has attracted the most attention in obesity and T2D studies." (PMID 25612568, 2015). "We conducted a study to evaluate the interaction effect of IGF2BP2 and obesity on T2DM in a large case-control sample of Chinese population." (PMID 25062844, 2014). "However, recent studies have shown that IGF2BP2−/− mice exhibit resistance to diet-induced obesity and fatty liver." (PMID 38443347, 2024).
Obesity (continued). "Thus, our results are in line with previous studies, which demonstrated that IGF2BP2 deletion in mice improves glucose tolerance and insulin sensitivity and protects mice from diet-induced obesity and fatty liver." (PMID 35163144, 2022). "Finally, IGF2BP2 also contributes to obesity and T2D through its regulation of IGF2, which participates in the pathogenesis of these diseases." (PMID 35163144, 2022). "We hypothesize that obesity may modify the association between IGF2BP2 and T2DM—also called the interaction of IGF2BP2 and obesity with T2DM." (PMID 25062844, 2014). "Therefore, impaired IGF2BP2 expression levels may contribute to the development of metabolic disorders such as obesity and T2D through alterations in the function of the adipose tissue." (PMID 31333715, 2019). "As a multifunctional regulator, IGF2BP2 is probably involved in the pathogenesis of PCOS through different pathways and its upstream regulator, HMGA2, is attributed to initate the dysfunction of cell proliferation, which is also related to T2DM and obesity." (PMID 35293050, 2022).
acute myeloid leukemia (27 papers, 2020 to 2026). Acute myeloid leukemia (AML) is a group of neoplasms arising from precursor cells committed to the myeloid cell-line differentiation. "In addition, in patients with acute myelocytic leukemia, the overexpression of IGF2BP2 indicates poor survival, and IGF2BP2 expression is associated with mutations in FLT3-ITD and IDH1, which are also indicators of poor prognosis." (PMID 33628845, 2021). "Furthermore, higher expression of IGF2BP2 was significantly associated with poor prognosis in acute myelocytic leukemia." (PMID 32784624, 2020). "For example, the m6A-binding protein IGF2BP2 is highly expressed in acute myeloid leukemia (AML) and is associated with poor prognosis." (PMID 39281280, 2024). "Knockdown of LINC00987 suppresses acute myeloid leukemia progression by inhibiting the IGF2BP2‐mediated PA2G4 expression." (PMID 36606322, 2023). "This phenomenon suggests that IGF2BP2 can affect the progression of FLT3-ITD + acute myeloid leukemia." (PMID 37060505, 2023). "In addition, IGF2BP2 has been reported to participate in the regulation of CSCs in acute myeloid leukemia (AML)." (PMID 36686749, 2022). "Acute myelocytic leukemia patients with high expression of IGF2BP2 had worse overall survival." (PMID 34976013, 2021). "IGF2BP2, an m6A binding protein that enhances the stability and translation of mRNA, is highly expressed in acute myeloid leukemia AML cells and promotes leukemia progression by regulating the expression of MYC." (PMID 40830264, 2025). "In acute myelocytic leukemia (AML), IGF2BP2 maintains the function of human and murine leukemia stem cells (LSCs) via stabilizing PRMT6 mRNA in m6A-mediated manner(37." (PMID 41522349, 2026). "IGF2BP2 is highly expressed in acute myeloid leukemia (AML)." (PMID 40332101, 2025). "IGF2BP2 recruits proteins such as eIF4E and eIF3A to MYC, GPT2, and SLC1A5 mRNA, regulating glutamine metabolism in acute myeloid leukemia and modulating the immune response of macrophages through epigenetic reprogramming." (PMID 39726589, 2024). "IGF2BP2 improves PRMT6 expression for leukemia stem cell (LSC) maintenance and acute myeloid leukemia development via stabilizing its transcript in an m6A-dependent form." (PMID 37280679, 2023). "IGF2BP2 and IGF2BP3 augmented the stability of DDX21 mRNA in an m6A-dependent manner, followed by recruitment of transcription factor YBX1 by DDX21 on ULK1 gene promoter and elevated transcription of ULK1, which facilitates progression of acute myeloid leukemia." (PMID 39866844, 2025). "Furthermore, IGF2BP2 inhibitors, CWI1-1 and CWI1-2, have also been identified, with CWI1-2 (IC50 = 203.1-781.6 nM in leukemia cell lines) demonstrating stronger anti-tumor effects on acute myelocytic leukemia in vitro and in vivo." (PMID 37280679, 2023).
gastric cancer (26 papers, 2018 to 2026). A primary or metastatic malignant neoplasm involving the stomach. "Clinical analyses show that IGF2BP2 is significantly overexpressed in gastric cancer tissues, and its expression level is closely associated with tumor size and poor patient prognosis." (PMID 40469197, 2025). "In gastric cancer patients treated by first-line combinational therapy with epirubicin, oxaliplatin, and 5-fluorouracil, IGF2BP2 polymorphisms rs4402960 and rs6769511 are less common in patients with disease progression than in those with controlled disease." (PMID 29736175, 2018). "Moreover, high IGF2BP2 expression was associated with poorer overall survival in gastric cancer patients." (PMID 40469197, 2025). "In this study, the expression levels of γ-H2AX protein were assessed by immunoblotting in IGF2BP2-modified gastric cancer cell lines before and after exposure to radiation (4 Gy)." (PMID 40469197, 2025). "Our study also confirmed the abnormally high expression of IGF2BP2 in pathological tissues of gastric cancer, which further promotes tumor cell proliferation, migration, and radioresistance by affecting the cell cycle, apoptosis, and glycolysis." (PMID 40469197, 2025). "RNA pull-down assay demonstrated that IGF2BP2 was significantly enriched in MKN74 gastric cancer cells and predominantly bound to the CDS region of HIF1α mRNA." (PMID 40469197, 2025). "To investigate this, we treated MKN74 gastric cancer cells with a combination of IGF2BP2 silencing and radiation and measured intracellular ROS levels using fluorescence microscopy." (PMID 40469197, 2025). "Overexpressed in gastric cancer, circRHBDD1 was found to bind to IGF2BP2 and shield it from ubiquitination and degradation by interfering with its interaction with the E3 ligase TRIM25." (PMID 40141058, 2025). "The m6A RNA modifications and their regulators—including METTL3, ALKBH5, FTO, YTHDFs, hnRNPA2B1, and IGF2BP2—have particularly emerged as key drivers of chemotherapy resistance in gastric cancer." (PMID 41228380, 2025). "The stability of CSF2 mRNA depends on the m6A reader IGF2BP2, which is highly expressed in gastric cancer tissues." (PMID 39791162, 2025). "IHC staining revealed that IGF2BP2 was significantly overexpressed in gastric cancer tissues, with high expression observed in 71.25% (57 out of 80) of tumor samples compared to the matched adjacent tissues." (PMID 40469197, 2025). "Functional studies demonstrate that elevated expression of IGF2BP2 accelerates the transition of gastric cancer cells from the G1 phase to the G2/M phase of the cell cycle and markedly enhances cell proliferation and migration through anti-apoptotic effects." (PMID 40469197, 2025). "CircRHBDD1, which is markedly upregulated in gastric cancer tissues, enhances PD-L1 mRNA stability by directly interacting with the RNA-binding protein IGF2BP2 in an m6A-dependent manner." (PMID 41229433, 2025). "Among these m6A “readers”, YTHDF1/2 and IGF2BP2/3 regulate mRNA stabilization and translation of stemness-related genes in gastric cancer." (PMID 41228380, 2025). "Our study supports these findings by demonstrating that regulation of HIF1α expression and lactate production in gastric cancer by the methylated reading protein IGF2BP2 exerts a radiosensitizing effect." (PMID 40469197, 2025). "Collectively, these results suggest an important role of IGF2BP2/CSF2/Notch1 axis in regulating MSCs reprogramming in gastric cancer." (PMID 37865637, 2023). "Collectively, these findings indicate that IGF2BP2/CSF2/Notch1 axis reprograms MSCs to promote gastric cancer progression." (PMID 37865637, 2023). "Correspondingly, co-inhibition of Notch1 in P-MSCs reversed the effects of IGF2BP2 knockdown on MSCs reprogramming, as well as the effects of their supernatants on gastric cancer cell proliferation, migration, and drug resistance." (PMID 37865637, 2023).
gastric cancer (continued). "In contrast, knockdown of IGF2BP2 in P-MSCs resulted in a diminution of its promoting effect on gastric cancer cell proliferation, migration, and drug resistance." (PMID 37865637, 2023). "The positive rate of IGF2BP2 was approximately 55% in gastric cancer patients who experienced relapse within 1 year after surgery, while it was approximately 17% in patients without recurrence within 3 years." (PMID 37865637, 2023). "In this study, we provided evidence showing that MSCs can be reprogrammed towards a pro-tumor phenotype by gastric cancer cells through an epigenetic mechanism, which involves increased IGF2BP2-mediated m6A modification and stability of CSF2 mRNA." (PMID 37865637, 2023). "Compared to control MSC group, the supernatant from IGF2BP2 overexpression MSCs group promoted the proliferation, migration, and drug resistance of gastric cancer cells." (PMID 37865637, 2023). "TCGA data analysis showed an increased expression of IGF2BP2 in gastric cancer tissues compared to normal tissues." (PMID 37865637, 2023). "In gastric cancer, IGF2BP2 rs4402960 and rs6769511 are more often detected in patients responsive to a combinational chemotherapy of epirubicin, oxaliplatin, and 5-fluorouracil." (PMID 29736175, 2018). "For instance, circRHBDD1 interacted with IGF2BP2 to induce immune escape in gastric cancer." (PMID 41439029, 2026). "Elevated expression of IGF2BP2 promotes the stabilization and translation of HIF1α mRNA in an m6A-dependent manner, thereby enhancing glucose metabolism and radiotherapy resistance in gastric cancer." (PMID 40469197, 2025). "IGF2BP2 may be a molecular indicator for predicting radiosensitization and even the efficacy of radiotherapy in gastric cancer." (PMID 40469197, 2025). "In our recent research, we found that exosomal Thrombospondin 1 (THBS1) derived from gastric cancer (GC) cells regulates METTL3- or IGF2BP2-mediated m6A modification, activating the RIG-I-like receptor signaling pathway in Vγ9Vδ2 T cells, thereby enhancing their cytotoxicity against GC cells." (PMID 39987091, 2025). "Together with our current findings, developing compounds that specifically inhibit IGF2BP2–HIF1α interaction may emerge as a novel therapeutic strategy for gastric cancer." (PMID 40469197, 2025). "Our study helps to deepen our understanding of cancer radiotherapy resistance, provides a new theoretical basis for the study of radiosensitization therapy for gastric cancer, and lays the foundation for the design of IGF2BP2-specific inhibitors for future intervention in gastric cancer." (PMID 40469197, 2025). "In addition, both METTL3 and IGF2BP2 are positively correlated with STAT5A in human gastric cancer tissue samples." (PMID 38879589, 2024). "In addition, IGF2BP2 knockdown in P-MSCs significantly suppressed their tropism towards gastric cancer cells and decreased FAP and α-SMA expression in P-MSCs." (PMID 37865637, 2023). "Furthermore, the introduction of Notch1 also curbed the augmentation of gastric cancer cell proliferation, migration, and drug resistance by the supernatant from IGF2BP2 overexpression MSCs." (PMID 37865637, 2023). "IGF2BP2 overexpression in MSCs resulted in increased tropism towards gastric cancer cells." (PMID 37865637, 2023). "Furthermore, the expression of IGF2BP2 positively correlated with that of CSF2 in gastric cancer tissues with a correlation coefficient of 0.54." (PMID 37865637, 2023). "Hence, these findings indicate that CSF2 acts as a downstream target of IGF2BP2 to promote the reprogramming of MSCs in gastric cancer." (PMID 37865637, 2023). "Similarly, LINC01559 can enhance the stability of ZEB1 mRNA by recruiting IGF2BP2, accelerate the proliferation and migration of gastric cancer cells, and promote the malignant development of gastric cancer." (PMID 38040698, 2023).
gastric cancer (continued). "In this project, by analyzing data from public databases and performing the immunohistochemical staining of clinical specimens, the level of IGF2BP2 was verified to be remarkably improved in gastric cancer tissues, and its overexpression predicted worse survival for GC patients." (PMID 36358799, 2022). "However, the specific effects of IGF2BP2 on gastric cancer (GC) and the underlying mechanisms remain unclear." (PMID 36358799, 2022). "Combining these findings, we inferred that elevated IGF2BP2 expression could predict poor prognosis in patients with gastric cancer." (PMID 36358799, 2022). "This study reveals the core mechanism by which insulin-like growth factor 2 mRNA-binding protein 2 (IGF2BP2) drives tumor progression and radiotherapy resistance in gastric cancer (GC) through m6A-dependent regulation of hypoxia-inducible factor 1α (HIF1α)." (PMID 40469197, 2025). "Our study highlights a critical role of IGF2BP2-mediated m6A modification of CSF2 in reprogramming MSCs, which presents a promising therapeutic target for gastric cancer." (PMID 37865637, 2023). "We next aimed to elucidate the involvement of IGF2BP2/CSF2/Notch1 axis in regulating the phenotype and function of MSCs in gastric cancer." (PMID 37865637, 2023). "Lung cancer and gastric cancer each had a single gene (YTHDF2 and IGF2BP2, respectively) enriched in tumor cells." (PMID 35794212, 2022). "Recently, LINC01559 was found to recruit IGF2BP2 to stabilize ZEB1 expression and accelerate gastric cancer cell proliferation, migration and EMT." (PMID 35299748, 2022). "A different six-antigen panel, including CTAG1B/CTAG2, DDX53, IGF2BP2, P53P53, and MAGEA3, detected 13% of gastric cancer patients." (PMID 33672007, 2021). "To investigate the expression of IGF2BP2, we performed IHC analysis on 80 paired gastric cancer and adjacent non-tumor tissue specimens." (PMID 40469197, 2025). "Furthermore, circRHBDD1 promotes immune evasion by enhancing IGF2BP2-mediated stabilization of PD-L1 transcripts, thereby reducing CD8+ T-cell infiltration in gastric cancer." (PMID 41229433, 2025). "Collectively, these findings further confirm the regulatory role of the IGF2BP2–HIF1α–glycolysis axis in gastric cancer metabolism and suggest that this mechanism is not affected by radiation exposure." (PMID 40469197, 2025). "Notably, overexpression of IGF2BP2 mimicked the effect of CSF2 on MSCs, promoting gastric cancer progression." (PMID 37865637, 2023). "Notably, IGF2BP2 has been found to target SIRT1, ZEB1, and HMGA1, thereby promoting gastric cancer growth and metastasis." (PMID 37865637, 2023). "The identified IGF2BP2/CSF2/Notch1 axis provides additional evidence for the epigenetic regulation of MSCs within the tumor microenvironment and offers a new therapeutic strategy for gastric cancer." (PMID 37865637, 2023). "Additionally, we demonstrated that the m6A reader IGF2BP2 bound to and stabilized CSF2 mRNA in gastric cancer MSCs." (PMID 37865637, 2023). "IGF2BP2 activates the RhoA-ROCK pathway by recognizing the m6A methylation site on insulin-like growth factor 1 receptor(IGF1R) mRNA, enhancing the proliferation, migration, and invasion of gastric cancer cells while reducing their tendency to undergo apoptosis." (PMID 39791162, 2025). "To explore the role of IGF2BP2 in the malignant progression of gastric cancer (GC) cells, we used MKN74 cells for IGF2BP2 silencing and HGC-27 cells for IGF2BP2 overexpression." (PMID 40469197, 2025).